ZNF614 (zinc finger protein 614)
Description:
May be involved in transcriptional regulation.
Synonyms: FLJ21941
Tractability: PROTAC: ubiquitination databases record sites on it.
Gene: Protein-coding gene on chromosome 19 (52,012,765 to 52,030,240, reverse strand). Ensembl gene ENSG00000142556.
Subcellular location: Nucleus
Subcellular location (Human Protein Atlas): Nucleoplasm; Cytosol; Vesicles
Pathways (Reactome):
Gene expression (Transcription): Generic Transcription Pathway
Gene Ontology:
Molecular function: protein binding; DNA-binding transcription factor activity, RNA polymerase II-specific; RNA polymerase II transcription regulatory region sequence-specific DNA binding; sequence-specific DNA binding
Biological process: regulation of transcription by RNA polymerase II; regulation of DNA-templated transcription
Cellular component: nucleus
Genetic constraint (gnomAD): Loss-of-function variants: 11 observed, 13.49 expected, observed/expected ratio (o/e) 0.82, 90% interval 0.51 to 1.35. The upper end of that interval is the gene's LOEUF score, 1.35, which puts it in group 5 of 6, group 1 being the genes least tolerant of losing a copy. Missense variants: 664 observed, 738.63 expected, observed/expected ratio (o/e) 0.9, 90% interval 0.84 to 0.96. Synonymous variants: 237 observed, 249.16 expected, observed/expected ratio (o/e) 0.95, 90% interval 0.86 to 1.06.
Homologues: Orthologues: chimpanzee ZNF614 (99% identical), macaque ZNF614 (97% identical), pig ZNF614 (74% identical), Drosophila melanogaster CG3281 (23% identical), Drosophila melanogaster Phs (20% identical), Drosophila melanogaster CG2712 (19% identical). Paralogues in human: ZNF674 (42% identical), ZFP90 (40% identical), ZFP37 (39% identical), ZNF805 (38% identical), ZNF582 (37% identical), ZNF25 (37% identical), ZNF133 (37% identical), ZNF264 (37% identical), ZNF875 (36% identical), ZNF343 (36% identical), ZNF266 (35% identical), ZNF169 (35% identical), and 50 more.
Diseases named in the same sentence as ZNF614 in open-access papers:
ZNF614 is named in the same sentence as 2 diseases in open-access papers, as found by Europe PMC text mining. Sharing a sentence is not in itself a finding about the gene and the disease. The quoted sentences say what the papers report.
depression (1 paper, 2025). "Furthermore, methylation at FTL_cg04385818 (OR = 0.295, 95% CI [0.094–0.925]) and ZNF614_cg09503196 (OR = 0.272, 95% CI [0.086–0.856]) were both associated with reduced odds of depression, supporting their potential protective roles." (PMID 41274868, 2025).
cancer (3 papers, 2022 to 2025). A tumor composed of atypical neoplastic, often pleomorphic cells that invade other tissues. "Several genes from the zinc finger family, including ZNF577, ZNF649, ZNF615, ZNF614, and ZNF432, are under intense investigation due to their altered methylation status in various cancer types." (PMID 36553064, 2022).